GFAP (glial fibrillary acidic protein)
Diseases named in the same sentence as GFAP in open-access papers (continued):
Sharing a sentence is not in itself a finding about the gene and the disease.
glioblastoma (continued). "IF was performed to observe the co-localization of the IL-1β and IL-18 pro-inflammatory cytokines with the GFAP glioblastoma marker." (PMID 35042538, 2022). "The established PD-GBOs shared known morphological features of glioblastoma including the presence of GFAP and nestin-labeled tumor microtubes (TMs), extensions that connect individual glioblastoma tumor cells to each other." (PMID 35743016, 2022). "Given the loss of GFAP and the expression of synaptophysin and CD56 in the new clival biopsy, the tumor did certainly show the immunohistochemical features of a glioblastoma with a neuronal component." (PMID 36414742, 2022). "Silencing of miR-1275 induces GFAP (an astrocyte marker) expression in glioblastoma cells, and its down-regulation was associated with oligodendroglia differentiation of tumour cells – similarly in our dataset this miRNA is down-regulated." (PMID 36412091, 2022). "Two other IF proteins were also analyzed in these glioblastoma cell lines: glial fibrillary acidic protein (GFAP) and nestin." (PMID 35701472, 2022). "This cell-adhesion molecule has been found to colocalize with subpopulations of GFAP+ reactive astrocytes in mouse models of brain injury and glioblastoma." (PMID 35592112, 2022). "Despite moderate GFAP positivity, it is therefore reasonable to diagnose a glioblastoma with a neuronal component in the temporal lobe biopsy as well." (PMID 36414742, 2022). "Curcumin activated autophagy and triggered the differentiation cascade of human glioblastoma by producing higher levels of βIII-tubulin and GFAP expression." (PMID 34370752, 2021). "Blood monocytes carrying glial fibrillary acidic protein have a high sensitivity and specificity for the detection of brain lesions and for glioblastoma patients with a decreased overall survival." (PMID 33501422, 2021). "For three samples, GFAP-positive areas within the same tumor also clustered to distinct subtypes of IDH-wildtype glioblastoma." (PMID 33876327, 2021). "Glial fibrillary acidic protein (GFAP) and Tau were used as biomarkers to characterize meningioma, brain metastasis, and glioblastomas." (PMID 33191521, 2021). "Since healthy cells of the brain parenchyma cannot be cultured under these cultivation conditions, GFAP and S100B can be used as markers for tumor cells in primary glioblastoma cell lines." (PMID 33251771, 2021). "In this research, the GFAP promoter was applied to control the expression of the HSVtk gene in glioblastoma cell lines, while the cytotoxicity of GCV was limited in neurons and fibroblasts." (PMID 34370752, 2021). "Based on the immunocytochemical validation criterion of a coexpression of GFAP and S100B, 15 out of these 16 cell lines (94%) were defined as primary glioblastoma cell lines (pGCL)." (PMID 33251771, 2021). "Fifteen out of the 16 primary cell lines (94%) were characterized, retained the expression of GFAP and S100B as reliable markers of astrocytic or glial cells, and were defined as primary glioblastoma cell lines (pGCL)." (PMID 33251771, 2021). "The proportion of GFAP positive cells in the primary glioblastoma cell lines, however, varied considerably." (PMID 33251771, 2021). "In this study, the GFAP promoter, an astrocyte-specific promoter, was used to restrict HSVtk gene expression in the glioblastoma cell line, U251." (PMID 34370752, 2021). "As validation criterion, we have defined that all cell lines with an immunopositivity for both markers GFAP and S100B are primary glioblastoma cell lines (pGCL)." (PMID 33251771, 2021). "This study established pGFAP-HSVtk-P2A-EGFP plasmids that successfully ablated GFAP-positive glioblastoma cells, but left neuronal N2A cells intact." (PMID 34370752, 2021). "High LCN2 and GFAP levels were also observed in tumor tissues from glioblastoma patients as compared to control brain tissues." (PMID 33171886, 2020).
glioblastoma (continued). "If cells such as astrocytes, GFAP + NP, radial glia, and GFAP + NSC are the origin of glioblastomas, then pro-proliferative role of oncogenes such as EGFRvIII appears to be more rational at least based on in vitro observations." (PMID 32774372, 2020). "And the diagnosis of extracranial metastasis (ECM) from glioblastoma can be achieved through clinical history, imaging findings, pathological examination, and immunohistochemical staining with GFAP." (PMID 32736607, 2020). "For example, the combination of GFAP, EMA, S-100 and vimentin was used to assist epithelioid glioblastoma (Ep-GBM) which is one provisional new variant of glioblastoma added to the WHO 2016 classification." (PMID 31968004, 2020). "Immunocytochemical images show the expression of glial fibrillary acidic protein (GFAP), a biomarker of astrocytes, in human U87 MG glioblastoma cells." (PMID 32182968, 2020). "In summary, the patterns of FN1 and GFAP correlated genes, a glioblastoma mesenchymal subtype signature, and the Matrigel invasion capacity indicate that U-343 MG has a more mesenchymal phenotype compared to the U-343 MGa cultures." (PMID 32642713, 2020). "In this study, we showed that GFAP, a biomarker of astrocytes, was expressed in human U87 MG glioblastoma cells." (PMID 32182968, 2020). "Given the history of glioblastoma, immunohistochemical staining with GFAP was performed to exclude the possibility of metastatic glioblastoma." (PMID 32736607, 2020). "We then double-stained Ki67 and GFAP in C6 and N/G cells and found that all three compounds decreased Ki67-possitive proliferating cells in C6 as well as U-87MG glioblastoma cells." (PMID 33162824, 2020). "First, while GFAP and Tau are elevated in patients who present with glioblastoma, all these patients are afflicted with sizable tumor by the time of presentation." (PMID 31311947, 2019). "Our study indicates that cell lines derived from glioblastoma, meningioma, and brain metastasis secrete EVs enriched for GFAP and Tau proteins." (PMID 31311947, 2019). "Apart from SOX2, glioblastoma cells also express GFAP, which can be considered quite surprising as GFAP for many years has been considered a marker of mature astrocytes." (PMID 32089685, 2019). "EV GFAP fluorescence exceeding 1.7 rIF had a sensitivity of 93% and specificity of 38% for diagnosis of glioblastoma." (PMID 31311947, 2019). "CD133 and GFAP co-expression has been detected in glioneuronal tumors, glioblastoma cells, and activated B1 astrocytes." (PMID 29849507, 2018). "Both male and female tumors were characteristically large at the time of euthanasia and diagnosed as glioblastoma-like based on expression of glial fibrillary acidic protein, and standard histological features including invasion, necrosis and abundant mitoses." (PMID 29458417, 2018). "The final pathologic diagnosis was glioblastoma with diffuse and strong expression of glial fibrillary acid protein (GFAP) and S-100." (PMID 28347331, 2017). "Strong tumor homing of DAG was seen in P13 model of angiogenic glioblastoma, where the peptide co-localized with a subset of the GFAP-positive cells." (PMID 29123083, 2017). "Increased levels of glial-derived and/or TF+MPs are also noted in glioblastoma multiforme (GBM) patients both before and even more so after the neoplasm is treated, suggesting a contribution of TF+/GFAP-MPs to the risk of VTE." (PMID 28484717, 2017). "The cell growth kinetics, the expressions of glioblastoma TICs marker Nestin, the differentiation markers, GFAP and Tuj1, and the proliferation marker, Ki67 were very similar between the passage 1 and 10 glioblastoma TICs." (PMID 27549983, 2016).
glioblastoma (continued). "To confirm our clinical finding, we tested the distribution of glioblastoma subtypes in a GFAP-CreER; PtenloxP/loxP; Trp53loxP/loxP; Rb1loxP/loxP; Rbl1−/− GEMM model where glioblastoma can arise anywhere in the cerebrum." (PMID 27056901, 2016). "We next performed immunohistochemical analysis to investigate the expression levels of stemness (CD133, ABCG2) and differentiation-related markers (GFAP) in human glioblastoma tissues." (PMID 26563263, 2015). "Further support for the idea that C3 transcription in the CNS is indeed driven by C/EBPD was obtained by ectopic expression of C/EBPD in the human glioblastoma cell line U-373 MG, which expresses the astrocyte marker GFAP." (PMID 26230261, 2015). "We found that in glioblastomas, highly malignant brain tumors, Akirin-2 and Twist-1 were expressed in glial fibrillary acidic protein positive tumor regions as well as in tumor endothelial cells and infiltrating macrophages / microglia." (PMID 26036627, 2015). "Incubation of glioblastoma stem cells with CTGF protein increased the expression of GFAP and a decrease of Sox2 proteins, indicating an increase in the differentiation rate of these cells." (PMID 26241738, 2015). "In human studies, it has been shown that the expression of GFAP is increased in the serum of patients with glioblastomas compared to other groups of patients with neural tumours and healthy ones." (PMID 26116110, 2014). "Glioblastomas are the most malignant neuroepithelial tumors of the brain, and typically express glial fibrillary acidic protein (GFAP)." (PMID 24348834, 2014). "Glioblastoma subpheres analysis revealed that most CD133 isolated cells co-expressed GFAP and Nestin, relating the isolated cells with neural and stem cell origin." (PMID 24432012, 2014). "We showed that HRasV12/AKT expression under CAG or GFAP promoter induced similar tumors, glioblastoma multiforme (WHO grade 4)." (PMID 25594049, 2014). "GFAP, a specific marker for immature or neoplastic astrocytes, is usually expressed in glioblastoma cells." (PMID 24348834, 2014). "The putative glioblastoma biomarker glial fibrillary acidic protein (GFAP) was also measured in the blood serum." (PMID 26116110, 2014). "This study revealed that CD133+ glioblastoma cells expressed high levels of nestin but expressed low levels of GFAP and NSE." (PMID 23251243, 2013). "By contrast, CD133− glioblastoma cells expressed low levels of nestin (0.47±0.06%), but had high expression levels of GFAP (77.41±8.49%) and NSE." (PMID 23251243, 2013). "In most human glioblastoma tumors, the bulk of the cells are GFAP-positive, indicating that differentiation occurs primarily along the astrocytic lineage." (PMID 23907540, 2013). "Over expressed in glioblastoma and localized to the surface of GFAP, normally expressed by neurons and oligodendrocytes." (PMID 23521751, 2013). "In CD133+ glioblastoma cells, the nestin-positive expression rate was 97.34±2.14%, GFAP was 1.44±0.27% and NSE was 1.35±0.24%." (PMID 23251243, 2013). "Studies utilizing an adapted retrovirus-mediated gene delivery system and an established human glioblastoma U373.MG cell line derivative expressing HIV-1 Tat show HIV-1 Tat produced successful induction of GFAP in a human glioblastoma U373.MG cell line." (PMID 22591363, 2012). "Tumour stem cells from glioblastoma differentiated into cells expressing mature neuronal and glial markers, TuJ1 and GFAP, respectively." (PMID 22262958, 2012). "The glial fibrillary acidic protein is a protein of the cytoskeleton and because of its high expression in astroglial tumours, such as astrocytoma and glioblastoma, it is used as a tumour marker." (PMID 21573151, 2011). "We also analyzed an array of 63 glioblastoma tissue sections that were glial fibrillary acidic protein (GFAP) positive; of 63 sections analyzed, 11 sections demonstrated anti-LPP3-RGD antibody immunoreactivity." (PMID 21569306, 2011).
glioblastoma (continued). "Next, we replaced the serum-starvation medium with neural differentiation medium in GFAP+NNP cultures as well as glioblastoma cell aggregates." (PMID 19216795, 2009). "Cells isolated from eight glioblastomas, as well as GFAP+NNP, were grown in the same culture conditions: first in expansion medium, then in serum-starvation medium, and finally in neural differentiation medium, as described in Materials and methods." (PMID 19216795, 2009). "In vitro differentiation of cancer cells derived from eight glioblastomas was compared with GFAP-positive normal neural progenitors (GFAP+NNP)." (PMID 19216795, 2009). "Glioblastoma cells forming aggregates, as well as undifferentiated GFAP+NNP, co-expressed SOX-2, Nestin, Beta III-tubulin, MAP2, GFAP, Vimentin, Fibronectin and CD44, when cultured under serum-starvation media." (PMID 19216795, 2009). "In this scenario perhaps "neural crest-like to mesenchymal transition", instead of mesenchymal differentiation of glioblastoma cells, would be more appropriate to convey the connection between glioblastoma cells and multipotent GFAP+NNP." (PMID 19216795, 2009). "The mesenchymal differentiation of glioblastoma cells is advanced and similar to mesenchymal differentiation of normal neural progenitors GFAP+NNP." (PMID 19216795, 2009). "Following methods were used to compare glioblastoma cells and GFAP+NNP (NHA): exposure to neural differentiation medium, exposure to adipogenic and osteogenic medium, western blot analysis, immunocytochemistry, single cell assay, BrdU incorporation assay." (PMID 19216795, 2009). "One discrepancy between glioblastoma cells and GFAP+NNP was sustained Nestin expression in neural derivatives of glioblastoma cells." (PMID 19216795, 2009). "Expression of c-Myc driven by the glial fibrillary acidic protein (GFAP)-promoter in developing mouse astroglia induces tumors that resemble human glioblastoma multiforme." (PMID 19020659, 2008). "The tumor displayed pathologic features initially suggestive of glioblastoma, including diffuse but atypical glial fibrillary acidic protein (GFAP) expression, positive but weak oligodendrocyte transcription factor 2 (Olig2) staining, high mitotic activity, and pseudopalisading necrosis." (PMID 42211592, 2026). "Background/Objectives: The study aimed to determine the expression of carcinogenesis-related genes, such as SLC12A2, SLC12A5, CDH1, CDH2, EZH2, and GFAP, in primary glioblastoma (WHO Grade IV; IDH-wild-type) cells from three adult women: GBM5-1, GBM5-2F, and GBM5-3F." (PMID 41012498, 2025). "The glioblastoma-like type exhibits massive expression of glial fibrillary acidic protein (GFAP)." (PMID 40361492, 2025). "Importantly, this modulation sensitizes glioblastoma cells to treatment while protecting normal astrocytes, where CoQ10 preserves glial fibrillary acidic protein integrity against radiation damage." (PMID 41009025, 2025). "We then compared the intratumoural distribution of blood flow as measured using [14C]iodoantipyrine, the expression pattern of B1R, and the presence of glioblastoma cells, as indicated by the glial fibrillary acidic protein (GFAP) marker expressed in astroglial tumours." (PMID 39065752, 2024). "In this field of view, B1R-positive cells colocalised with GFAP-positive glioblastoma cells." (PMID 39065752, 2024).
glioblastoma (continued). "Another factor by which hydrogen may increase its cellular proliferation is its ability to activate GFAP (glial fibrillary acidic protein), a marker of differentiation in glioblastoma cells." (PMID 36978884, 2023). "Recent emerging evidence supports the involvement of GFAP in glioblastoma multiforme (GBM)." (PMID 36959545, 2023). "To validate the data from bulk mRNA seq, we selected a set of neural and glial‐specific genes (i.e., PAX6, BRN2/POU3F2, NF‐L/NEFL, and GFAP) showing high expression in the GLICO model in comparison to independently cultured glioblastoma spheroids or standard glioblastoma 2D culture." (PMID 36744875, 2023). "In addition, TMEM132A is also reported to regulate the expression of cAMP-induced glial fibrillary acidic protein in rat C6 glioblastoma cells." (PMID 35501731, 2022). "The regulation of histone acetylation has an essential role in glioblastoma and could be a promising target by reducing GFAP total expression." (PMID 35372061, 2022). "We demonstrated that this system could selectively ablate GFAP-positive glioblastoma cell lines, while it left the neuronal N2A cells intact and promoted neural differentiation after challenge with the HSVtk/GCV system." (PMID 34370752, 2021). "Furthermore, rapamycin, a therapeutic agent with both immunosuppressant and antitumor properties, reduced the proliferation of glioblastoma cells and increased the expression of neural differentiation markers (GFAP and βIII-tubulin)." (PMID 34370752, 2021). "In the present study, we confirmed that the GFAP promoter could specifically control HSVtk expression in glioblastoma cell lines while leaving neuronal cell lines intact." (PMID 34370752, 2021). "A study showed GFAP was generally strong in both low grade astrocytomas and glioblastomas." (PMID 33391433, 2021). "However, the proportion of GFAP‐expressing cells varied markedly in the primary glioblastoma cell lines: in 3/15 pGCL, it was high (>50%), in 8/15 pGCL, medium, and in 4/15 pGCL, low (≤10%)." (PMID 33251771, 2021). "Therefore, in this study, we aimed to establish a plasmid encoding the HSVtk/GCV system driven by a glial fibrillary acidic protein (GFAP) promoter and verify its possibility of neural differentiation of glioblastoma cell line under the GCV challenge." (PMID 34370752, 2021). "These two glioblastoma subpopulations expressed a distinct difference in nestin and GFAP transmembrane expression, respectively, which may have led to the distinct DEP characteristics." (PMID 33191521, 2021). "The HSVtk/GCV system driven by the GFAP promoter could ablate GFAP-positive glioblastoma cell lines and promote neural differentiation within 5 days of GCV treatment." (PMID 34370752, 2021). "The immunoprofile of the glial marker GFAP in glioblastomas is similar to astrocytomas." (PMID 33251771, 2021). "In conclusion, this study established pGFAP-HSVtk-P2A-EGFP plasmids that could successfully ablate GFAP-positive glioblastoma cell lines, while neuronal N2A cells remained intact." (PMID 34370752, 2021). "Therefore, the expression of malignancy and proliferation markers in combination to the proportion of GFAP and S100B expression should be assessed to define the usefulness of self‐established glioblastoma cell lines for further experiments." (PMID 33251771, 2021). "Applying the defined validation criterion, expression of both markers GFAP and S100B, 15 primary glioblastoma cell lines (pGCL) could be establish from 34 intraoperative glioblastoma samples processed in this study, resulting in a total efficiency of 44%." (PMID 33251771, 2021). "In glioblastoma patients, SAO are independently associated with younger age, better preoperative clinical performance, certain tumor characteristics (location in the parietal lobe and higher GFAP expression), and serum ion alterations (higher chloride levels)." (PMID 33506201, 2021). "Glioblastoma is astrocytic tumor and GFAP is a cell-type specific marker for astrocytes." (PMID 33162824, 2020).